MNS1 (meiosis specific nuclear structural 1)
Description:
Microtubule inner protein (MIP) part of the dynein-decorated doublet microtubules (DMTs) in cilia axoneme, which is required for motile cilia beating. May play a role in the control of meiotic division and germ cell differentiation through regulation of pairing and recombination during meiosis. Required for sperm flagella assembly (By similarity). May play a role in the assembly and function of the outer dynein arm-docking complex (ODA-DC). ODA-DC mediates outer dynein arms (ODA) binding onto the axonemal doublet microtubules.
Synonyms: CFAP127; FLJ11222; SPATA40; HTX9
Tractability: Small molecule: a structure with a bound ligand is known.
Target class: Structural protein
Gene: Protein-coding gene on chromosome 15 (56,421,544 to 56,465,168, reverse strand). Ensembl gene ENSG00000138587.
Subcellular location: Nucleus; Cytoplasm, cytoskeleton, cilium axoneme; Cytoplasm, cytoskeleton, flagellum axoneme
Subcellular location (Human Protein Atlas): End piece; Nuclear speckles; Nucleoplasm; Primary cilium; Basal body; Cytosol; Flagellar centriole; Perinuclear theca
Gene Ontology:
Molecular function: identical protein binding; protein binding
Biological process: cilium organization; flagellated sperm motility; positive regulation of cilium assembly; sperm axoneme assembly; spermatogenesis
Cellular component: axonemal microtubule; axoneme; cilium; sperm end piece; axonemal A tubule inner sheath; motile cilium; nucleus; sperm flagellum; intermediate filament; nuclear envelope; polymeric cytoskeletal fiber
Genetic constraint (gnomAD): Loss-of-function variants: 55 observed, 66.67 expected, observed/expected ratio (o/e) 0.82, 90% interval 0.66 to 1.03. The upper end of that interval is the gene's LOEUF score, 1.03, which puts it in group 4 of 6, group 1 being the genes least tolerant of losing a copy. Missense variants: 577 observed, 557.6 expected, observed/expected ratio (o/e) 1.03, 90% interval 0.97 to 1.11. Synonymous variants: 183 observed, 172.89 expected, observed/expected ratio (o/e) 1.06, 90% interval 0.94 to 1.2.
Gene-disease validity (ClinGen):
ClinGen rates the evidence that MNS1 causes each of these diseases.
primary ciliary dyskinesia (autosomal recessive): Disputed. A rare, genetically heterogeneous, primarily respiratory disorder characterized by chronic upper and lower respiratory tract disease.
Homologues: Orthologues: chimpanzee MNS1 (99% identical), macaque MNS1 (98% identical), dog MNS1 (90% identical), rabbit MNS1 (88% identical), pig MNS1 (87% identical), guinea pig MNS1 (86% identical), rat Mns1 (77% identical), mouse Mns1 (77% identical), tropical clawed frog mns1 (58% identical), zebrafish mns1 (51% identical).
Diseases named in the same sentence as MNS1 in open-access papers:
MNS1 is named in the same sentence as 31 diseases in open-access papers, as found by Europe PMC text mining. Sharing a sentence is not in itself a finding about the gene and the disease. The quoted sentences say what the papers report.
male infertility (7 papers, 2012 to 2025). The inability of the male to effect fertilization of an ovum after a specified period of unprotected intercourse. "In a more recent study, we identified a homozygous frameshift founder variant in MNS1 among four interrelated Amish families, which is associated with irregularities in left–right body asymmetry and male infertility." (PMID 38920647, 2024). "We previously defined biallelic MNS1 variants causing situs inversus and male infertility, mirroring the findings in Mns1−/− mice." (PMID 38920647, 2024). "We subsequently identified homozygous nonsense variants in MNS1 as a cause of situs inverus and male infertility in three families." (PMID 38920647, 2024). "Here we provide extensive co-segregation data and comprehensive clinical information of a homozygous MNS1 Amish founder gene variant [NM_018365.2:c.407_410del; p.(Glu136Glyfs*16)] as responsible for SI and/or male infertility." (PMID 31534215, 2020). "Subtle ODA defects have been reported in patients with mutations in MNS1 (meiosis specific nuclear structural 1), accompanied by male infertility, situs inversus and mild PCD symptoms." (PMID 31781811, 2020). "Overall, we demonstrate that MNS1 deficiency in humans causes laterality defects (situs inversus) and likely male infertility and that MNS1 plays a role in the ODA-DC assembly." (PMID 30148830, 2018). "MNS1 mutations are associated with the occurrence of situs inversus and male infertility." (PMID 37275875, 2023). "Lately, several genes have been reported to be associated with laterality defects, male infertility, and mild variable respiratory phenotypes such as CCDC11/CFAP53, ENKUR, WDR16/CFAP52, DAW1, and MNS1." (PMID 38920647, 2024). "Most individuals reported with MNS1-related motile ciliopathy to date have displayed laterality defects and/or male infertility." (PMID 38920647, 2024). "Further functional analyses regarding MNS1 function will help to better understand the molecular mechanisms involved in laterality defects as well as male infertility." (PMID 30148830, 2018). "Therefore, mutations in MNS1 may contribute to male infertility and PCD in humans." (PMID 22396656, 2012). "In summary, our study identifies a novel frameshift variant NM_018365.2:c.407_410del in MNS1 in association with SI and male infertility, without other features of PCD or ciliopathies." (PMID 31534215, 2020). "Therefore, our study of MNS1 has important implications for male infertility in humans." (PMID 22396656, 2012).
situs inversus (6 papers, 2012 to 2024). A congenital condition in which there is complete right-to-left reversal of the position of the major thoracic and abdominal organs (that is, they are arranged in a mirror image of the normal positioning). "The MNS1 c.724C>T, p.(Arg242*) nonsense variant identified in a homozygous state in three individuals in this study has been previously reported in four different male individuals who suffered only from situs inversus and infertility." (PMID 38920647, 2024). "Therefore, in addition to male sterility, MNS1-deficient mice exhibit situs inversus and hydrocephalus, suggesting an essential role for MNS1 in motile cilia function and implicating MNS1 in primary ciliary dyskinesia (PCD)." (PMID 22396656, 2012). "In addition, MNS1–deficient mice display situs inversus and hydrocephalus." (PMID 22396656, 2012). "However, eight of 22 Mns1−/− embryos examined (E12.5–E16.5) displayed normal situs, eight presented with situs inversus, and six exhibited left isomerism, indicating that MNS1 is required for nodal ciliary function." (PMID 22396656, 2012).
ciliopathies (3 papers, 2020 to 2025). "Ciliopathy panel testing and whole exome sequencing identified one previously reported and two novel MNS1 variants extending the genotypic spectrum of disease." (PMID 38920647, 2024). "The novel observations of heterotaxia, complex congenital heart disease, and variable respiratory symptoms in patients with biallelic MNS1 variants highlight the well-established clinical variability of motile ciliopathy disorders." (PMID 38920647, 2024). "Using either whole exome sequencing (Family EX-1) or targeted PCD gene panel sequencing encompassing all known PCD and motile ciliopathy-related genes at the time of investigation, we identified three affected males and two affected females associated with three MNS1 variants." (PMID 38920647, 2024). "The current study identifies a further four affected individuals and a fetus with MNS1-related motile ciliopathy from four families from Afghanistan, Egypt, and Kosovo." (PMID 38920647, 2024).
heart failure (3 papers, 2023 to 2025). Inability of the heart to pump blood at an adequate rate to meet tissue metabolic requirements. "Recent studies have revealed that MNS1 could be involved in the control of meiosis and germ cell differentiation, affecting the mating and recombination processes during meiosis, and serving as a diagnostic indicator in heart failure research." (PMID 40297163, 2025). "A recent study showed that MNS1 was screened through three machine learning methods to be regarded as a possible bioinformatics marker for heart failure." (PMID 36863704, 2023). "Ultimately, a total of four genes (FCN3, FREM1, MNS1, and SMOC2) exhibited significant co-expression in individuals suffering from heart failure." (PMID 40297163, 2025). "The meiosis-specific nuclear structural 1 (MNS1) gene is involved in bile acid, fatty acid, and haem metabolism and it affects the course of heart failure." (PMID 36863704, 2023). "Similar to MNS1, there is limited research on FREM1-specific functions in heart failure, but it is hypothesized to play roles in tissue remodeling and repair processes after myocardial injury." (PMID 40297163, 2025).
Infertility (3 papers, 2012 to 2024). "In 2018, we described biallelic pathogenic mutations in MNS1 associated with laterality defects and infertility in males." (PMID 38920647, 2024). "Here, we describe two loss-of-function variants in MNS1 in individuals suffering from laterality defects and infertility." (PMID 30148830, 2018). "Our findings on the function of MNS1 from mouse studies will help to select a cohort of infertile men with defined phenotypes for mutation screening in the human MNS1 gene." (PMID 22396656, 2012). "Thus, homozygous MNS1 mutations in humans result in laterality defects and likely cause infertility, consistent with the phenotype of Mns1-/- mouse." (PMID 30148830, 2018). "Further studies of the function of MNS1 may implicate new biological pathways affecting susceptibility to laterality defects and infertility." (PMID 30148830, 2018). "Interestingly, five males related to the reported individuals with MNS1 mutations (AL-III-9 and BG-II-1) suffered also from infertility, but these individuals were not included in our genetic analysis." (PMID 30148830, 2018).
fibrosarcoma (2 papers, 2018 to 2024). A malignant mesenchymal fibroblastic neoplasm affecting the soft tissue and bone. "Three proteins: ANXA5, ANXA3, and MNS1 were identified to be significantly (p ≤ 0.05) differentially expressed in doxorubicin-resistant fibrosarcomas in comparison to doxorubicin-sensitive ones." (PMID 29443940, 2018).
Situs inversus totalis (2 papers, 2018 to 2024). "X-ray analysis showed that OI-11II6 has situs inversus totalis, consistent with findings reported in Mns1-/- mice, in which the genetic defect causes randomization of left/right body asymmetry." (PMID 30148830, 2018). "Here we report the identification of LOF mutations in MNS1 in individuals with laterality defects ranging from situs inversus totalis to dextrocardia with congenitally corrected transposition of the great arteries and mitral atresia." (PMID 30148830, 2018).
chronic kidney disease (1 paper, 2025). Impairment of the renal function secondary to chronic kidney damage persisting for three or more months. "In the development of a diagnostic model for predicting DCM onset in chronic kidney disease patients, MNS1 and HERC6 emerged as significant model genes." (PMID 40520229, 2025).
chronic rhinitis (1 paper, 2024). Chronic inflammation of the nasal cavity mucosa. "Interestingly, a single affected six-year-old girl homozygous for an MNS1 nonsense variant presented with a history of neonatal respiratory distress syndrome, recurrent respiratory tract infections, chronic rhinitis, and wet cough." (PMID 38920647, 2024). "In this study, we identify for the first time a respiratory phenotype in association with MNS1-related motile ciliopathy with two males affected by mild symptoms including RDS, rhinitis, sinusitis, recurrent cough, and a female with a pronounced respiratory phenotype." (PMID 38920647, 2024).
colon cancer (1 paper, 2018). "The MNS1 gene was shown to be down-regulated in an oxaliplatin-resistant human colon cancer cell line, and up-regulated in an oxaliplatin-sensitive human colon cancer cell line after continuous treatment with oxaliplatin for 24 h, suggesting its molecular role in chemoresistance." (PMID 29443940, 2018).
dyslexia (1 paper, 2014). A learning disorder characterized by an impairment in processing written words. "Four out of the five most strongly associated genes in the GSEA of the GWAS study for relative hand skill in the dyslexia cohort are involved in ciliogenesis: meiosis-specific nuclear structural protein 1 (MNS1), regulatory factor X 3 (RFX3), GLI family zinc finger 3 (GLI3), as well as PKD2." (PMID 24275328, 2014).
Hydrocephalus (1 paper, 2012). Hydrocephalus is an active distension of the ventricular system of the brain resulting from inadequate passage of CSF from its point of production within the cerebral ventricles to its point of absorption into the systemic circulation. "MNS1–deficient mice also display defects in left–right asymmetry patterning of internal organs and hydrocephalus." (PMID 22396656, 2012). "In contrast with wild type mice, post-natal day 24-old Mns1−/− mice developed hydrocephalus, suggesting that MNS1 is also important for ependymal ciliary function." (PMID 22396656, 2012).
idiopathic dilated cardiomyopathy (1 paper, 2025). Decreased function of the heart associated with cardiac enlargement and congestive heart failure, of unknown cause. "For Idiopathic Dilated Cardiomyopathy (IDC), MNS1 and MYOT intersected between RFE and DEA and had high AUC." (PMID 40287491, 2025).
ischemic cardiomyopathy (1 paper, 2025). Ischemic cardiomyopathy is a cardiomyopathy in which a weakness in the muscle of the heart due to inadequate oxygen delivery to the myocardium with coronary artery disease being the most common cause. "Additionally, MNS1 has been shown to be highly expressed in patients with ischemic cardiomyopathy." (PMID 40520229, 2025).
Neonatal respiratory distress (1 paper, 2022). Respiratory difficulty as newborn. "Conversely, individuals with biallelic MNS1, DNAH9, CFAP53 or RSPH1 mutations have a lower prevalence of neonatal respiratory distress and a later and milder onset of respiratory symptoms." (PMID 36583018, 2022).
polycystic kidney disease (1 paper, 2012). A usually autosomal dominant and less frequently autosomal recessive genetic disorder characterized by the presence of numerous cysts in the kidneys leading to end-stage renal failure. "However, the MNS1-deficient mice lacked polycystic kidney disease and polydactyly, suggesting that MNS1 is not required for non-motile ciliary functions." (PMID 22396656, 2012).
cancer (4 papers, 2018 to 2025). A tumor composed of atypical neoplastic, often pleomorphic cells that invade other tissues. "Selective toxicity is critical in cancer therapy; to determine whether the MNS1 compounds selectively killed cancer cells with minimal toxicity to normal brain cells, we tested the MNS1 compounds with treatments ranging from 0.01–25 μM." (PMID 31361777, 2019). "Little is known on the role of MNS1 in cancer research and chemoresistance, as it is a coiled-coil protein of unknown function expressed in the pachytene stage of the spermatogenesis, in the diplotene spermatocytes, and in the spermatids that are essential for spermatogenesis." (PMID 29443940, 2018). "We further investigated how SCNA influences gene expression and found the expression of FCN3, FREM1, MNS1, and SMOC2 was significantly positively associated with SCNA in most cancers, which indicated that aberrant SCNA of a gene might contribute to the progression of various cancers." (PMID 40297163, 2025).
Tumor (3 papers, 2018 to 2022). "Tumor bearing mice were treated by oral gavage for 21 days with increasing concentrations of MNS1-Leu and tumor volume and bioluminescence increased in vehicle treated animals while tumors in drug treated animals did not." (PMID 31361777, 2019). "To validate the anti-tumor effects in vivo, we tested MNS1-Leu in a pediatric HGG PDX model (DIPG XVII, H3K27M)." (PMID 31361777, 2019). "The significantly lower expression of MNS1 in all of the tumours that were grown from doxorubicin-resistant cell lines in comparison to the doxorubicin-sensitive cell line indicates its role in primary MDR." (PMID 29443940, 2018). "Functional analysis showed that MNS1 compounds induced apoptosis and decrease tumor migration." (PMID 31361777, 2019). "Therefore, the primary objective of this study was to validate and assess feasibility of the anti-tumor properties of these MNS1 compounds in a series of patient-derived HGGs to provide the platform for further therapeutic advances in the management of these dismal diseases." (PMID 31361777, 2019). "Here we investigated the antitumor effects of novel pyrazole-based STAT3 pathway inhibitors named MNS1 (Mayo Neurosurgery 1) in both pediatric and adult HGG tumor cells." (PMID 31361777, 2019). "In our preliminary in vivo work, we did not observe any toxic sequelae of MNS1-Leu in a xenograft model despite an obvious decrease in tumor size, which highlights a favorable therapeutic profile." (PMID 31361777, 2019).
cardiac diseases (1 paper, 2025). "Collectively, these findings suggest that MNS1 may play a significant regulatory role in cardiac diseases; however, its specific relationship with DCM remains unclear." (PMID 40520229, 2025).
respiratory disease (1 paper, 2024). "This study represents the first observation of heterotaxia and respiratory disease in individuals with biallelic MNS1 variants, an important extension of the phenotype associated with MNS1-related motile ciliopathy disorder." (PMID 38920647, 2024).
MNS1 also shares sentences with these, for which no sentence is quoted: congenital heart defects (2 papers); asthenozoospermia (1); glioma (1); ischaemic cardiomyopathy (1); mitral atresia (1); neonatal respiratory distress syndrome (1); primary ciliary dyskinesia (1); respiratory infections (1); Respiratory tract infection (1); seminoma (1); sinusitis (1).